TBC1D24 (TBC1 domain family member 24)
Diseases named in the same sentence as TBC1D24 in open-access papers (continued):
Sharing a sentence is not in itself a finding about the gene and the disease.
hearing loss (16 papers, 2015 to 2024). "This provides some clues to investigate the pathogenic mechanism of hearing loss associated with mutations in the TBC1D24 gene, but more detailed clinical data are needed to validate this result." (PMID 38413761, 2024). "A novel heterozygous variant, c.1459C>T (p.His487Tyr), in the TBC1D24 gene was identified and confirmed to be associated with the hearing loss phenotype in this family." (PMID 38413761, 2024). "After a thorough investigation of the hearing-age correlation of TBC1D24 hereditary non-syndromic hearing loss, we found that the power model provided the best fit." (PMID 38413761, 2024). "Several TBC1D24 variants are causally involved in the development of profound, prelingual hearing loss (HL) and different epilepsy syndromes inherited in an autosomal recessive manner." (PMID 33986365, 2021). "Another example is pathogenic variants of TBC1D24 that are associated with non-syndromic hearing loss, segregating as a recessive (DFNB86) or a dominant trait (DFNA65)." (PMID 32987832, 2020). "In the last years, three publications reported mutations in TBC1D24 associated to non-syndromic hearing loss (NSHL)." (PMID 26371875, 2015). "TBC1D24 mutations cause severe-to-profound congenital autosomal recessive nonsyndromic sensorineural hearing loss, in addition to progressive dominant nonsyndromic sensorineural hearing loss." (PMID 36529647, 2022). "The human TBC1D24 p.His336Glnfs*12 variant is associated with syndromic hearing loss." (PMID 32987832, 2020). "In addition, TBC1D24 expression is also present in the cochlea in the inner and outer hair cells and in the spiral ganglion neurons, substantiating also why TBC1D24 mutations can induce hearing loss." (PMID 26371875, 2015). "Similar to most TBC1D24 mutations in DFNB86 cases with severe to profound sensorineural hearing impairment, our patient also presented with congenital severe hearing impairment." (PMID 33095980, 2020). "Similarly, OS is proposed to play a central role in hearing loss, in particular age-related forms; although it is unknown at present whether hearing loss-associated mutations affect the antioxidative function of TBC1D24." (PMID 28707022, 2017). "OXR1 contains the Tre2/Bub2/Cdc16 (TBC), lysin motif (LysM), domain catalytic (TLDc) domain, a motif present in a family of proteins including TBC1 domain family member 24 (TBC1D24), a protein mutated in a range of disorders characterized by seizures, hearing loss, and neurodegeneration." (PMID 26668325, 2016).
Epileptic encephalopathy (14 papers, 2015 to 2025). A condition in which epileptiform abnormalities are believed to contribute to the progressive disturbance in cerebral function. "The epileptic encephalopathy observed in individuals with TBC1D24 variants is characterized by frequent, refractory seizures, which can contribute to severe cognitive decline and developmental regression." (PMID 39596051, 2024). "Patients with TBC1D24 pathogenic variants often present with a combination of epileptic encephalopathy and neurodegenerative features, including cerebellar atrophy, which contributes to motor deficits such as ataxia and dystonia." (PMID 39596051, 2024). "Here, we show that the epileptic encephalopathy-associated protein Tbc1d24 forms cytoophidia in neuronal cells both in vitro and in vivo." (PMID 33886577, 2021). "Mutations in TBC1D24 cause the refractory seizure syndrome called epileptic encephalopathy (EE)." (PMID 33886577, 2021). "TBC1D24 is a pleiotropic gene associated with recessive DOORS syndrome, epileptic encephalopathy, myoclonic epilepsy, and both recessive and dominant hearing impairment." (PMID 33281559, 2020). "The top-ranked probes related to 25 genes including HNRNPL, RASSF5, CD3D and KALRN involved in immune signalling pathways, in addition to TBC1D24, FBXO9 and VIPR2 previously linked to epileptic encephalopathy." (PMID 29484035, 2018). "Neurodegeneration is observed in lethal epileptic encephalopathy caused by TBC1D24 truncating mutation as well as in flies lacking Skywalker." (PMID 32004315, 2020).
onychodystrophy (14 papers, 2014 to 2024). "Mutations in the TBC1D24 gene cause hearing loss, genetic epilepsy, onychodystrophy, mental retardation, and seizures." (PMID 36529647, 2022).
DOORS syndrome (13 papers, 2014 to 2024). "Mutations disrupting presynapticprotein TBC1D24 are associated with a variable neurological phenotype, including DOORS syndrome, myoclonic epilepsy, early-infantile epileptic encephalopathy, and non-syndromic hearing loss." (PMID 28663785, 2017). "Mutations in TBC1D24 are also associated with DOORS syndrome, a rare disorder characterised by hearing loss and shortened terminal phalanges with small nails of the hands and feet, in addition to seizures and neurodevelopmental delay." (PMID 28707022, 2017). "Our findings suggest that mutations in TBC1D24 seem to be an important cause of DOORS syndrome and can cause diverse phenotypes." (PMID 24291220, 2014). "Annotations for all TBC1D24 variants (from DOORS syndrome, the other associated epileptic disorders, and the Exome Variant Server), including population frequency, conservation scores and PolyPhen2 scores are in the appendix (p 8)." (PMID 24291220, 2014). "If we stratify based on this strict definition of DOORS syndrome, TBC1D24 mutations were seen in nine of 18 families." (PMID 24291220, 2014). "Finally, these observations also have implications for the window that is available to therapeutically target the 5PPase domain of Synj1 in DS, AD, and TBC1D24-associated DOORS syndrome." (PMID 33349335, 2020). "However, phenotypic pleiotropy has rarely been reported to span the spectrum from seizures alone (eg, previous reports on TBC1D24 mutations) to multi-systemic syndromic disorders such as DOORS syndrome." (PMID 24291220, 2014). "We have identified mutations in TBC1D24 as a probable cause of DOORS syndrome." (PMID 24291220, 2014). "The diversity of seizure types seen in TBC1D24-associated epileptic syndromes and in DOORS syndrome is striking, and might point to a general epileptogenic mechanism." (PMID 24291220, 2014). "Interestingly, the clinical phenotype of TBC1D24 biallelic variants may overlap with that of ATP6V1B2 mutations, as both genes represent the major genetic cause of DOORS syndrome, implying a physiological link between TBC1D24 and v-ATPase function." (PMID 39273013, 2024). "For instance, dominant mutations in the TBC1D24 gene (MIM: 613577) have been identified to cause hearing loss, while recessive mutations in the same gene are associated with DOORS syndrome (HGMD)." (PMID 34912366, 2021). "Further research is needed to establish the precise role of TBC1D24 not only in the nervous system, but also in the skeletal system and other systems affected in DOORS syndrome." (PMID 24291220, 2014). "Using an antibody against TBC1D24, we studied expression in digital chondrocytes, in view of the distal phalangeal hypoplasia in DOORS syndrome and the high expression seen in chondrocytes in the Human Protein Atlas." (PMID 24291220, 2014). "The phenotypic similarity between patients with and without TBC1D24 mutations is highly suggestive of genetic heterogeneity in DOORS syndrome." (PMID 24291220, 2014). "Some individuals without TBC1D24 mutations had typical features of DOORS syndrome, including the more specific signs of triphalangeal thumbs and 2-oxoglutaric aciduria, and were clinically indistinguishable from those with TBC1D24 mutations." (PMID 24291220, 2014). "Five of the families with DOORS syndrome in our study have substitutions affecting the arginine at position 242, and two have substitutions affecting the arginine at position 40, suggesting that these residues are crucial in TBC1D24 function." (PMID 24291220, 2014).
Intellectual disability (9 papers, 2015 to 2023). "Previous characterization on patients with TBC1D24 gene mutations mostly focuses on seizure and intellectual disability." (PMID 32004315, 2020). "We focus on the hippocampus because of high TBC1D24 expression in this brain area and its importance in learning and memory, which is relevant since TBC1D24 mutations are associated with intellectual disability." (PMID 32004315, 2020). "Alteration of excitatory synapses due to loss of TBC1D24 expression may underlie the pathogenesis of TBC1D24 F251L mutation-associated intellectual disability." (PMID 32004315, 2020).
epilepsy syndrome (5 papers, 2014 to 2021). A syndrome that has a characteristic cluster of clinical features and/or lectroencephalographic (EEG) findings that reflect underlying epileptic activity. "Previously reported, but different, mutations in TBC1D24 cause various epileptic syndromes." (PMID 24291220, 2014). "TBC1D24, coding for TBC1 Domain Family Member 24, is a pleiotropic gene that has been associated with autosomal recessive (AR) HL (DFNB86), ADHL (DFNA65), and a range of epilepsy syndromes." (PMID 33281559, 2020). "Furthermore, TBC1D24 epilepsy syndromes occur with both compound heterozygous and homozygous recessive mutations." (PMID 27281533, 2016).
familial infantile myoclonic epilepsy (5 papers, 2011 to 2020). A rare, genetic, infantile epilepsy syndrome disease characterized by neonatal- to infancy-onset myoclonic focal seizures occurring in various members of a family, associated in some with mild dysarthria, ataxia and borderline-to-moderate intellectual disability. "Significantly, mutations in the TLDc domain of TBC1D24 are associated with Familial Infantile Myoclonic Epilepsy (FIME) and Progressive Myoclonic Epilepsy (PME)." (PMID 27036366, 2016). "Significantly, a mutation in the TLDc domain of TBC1D24 recently has been found in Familial Infantile Myoclonic Epilepsy (FIME)." (PMID 22028674, 2011). "The deletion region comprises TSC2, PKD1, TBC1D24 and ABCA3 genes and mutations of these genes are associated with tuberous sclerosis complex, autosomal dominant polycystic kidney disease type 1 (ADPKD1) or familial infantile myoclonic epilepsy." (PMID 31060568, 2019). "Consistent with this hypothesis, compound heterozygous mutations in TBC1D24, one in the TBC domain and another in the TLDc domain, cause familial infantile myoclonic epilepsy (FIME), whereas the parents carrying either one of these mutations are phenotypically normal." (PMID 26668325, 2016).
Seizure (5 papers, 2013 to 2024). A seizure is an intermittent abnormality of nervous system physiology characterized by a transient occurrence of signs and/or symptoms due to abnormal excessive or synchronous neuronal activity in the brain. "Polymorphisms in TBC1D24 have been associated with shortened axons and epileptic seizures." (PMID 23759029, 2013). "TBC1D24, the 24th member of the TBC1 domain family, was first discovered as a causative gene for epileptic seizures in an Italian family in 201023." (PMID 38413761, 2024).
breast carcinoma (3 papers, 2022 to 2023). "For instance, being associated with poor outcome in breast carcinoma, TBC1D24 promoted cell proliferation through IGF1R/PI3K/AKT pathway." (PMID 35574392, 2022). "TBC1D24 has been shown to play an important role in the proliferation, migration, and invasion of breast cancer cells." (PMID 35564499, 2022). "In addition, ROC analysis revealed that the four genes had higher AUC values for predicting the diagnosis of breast cancer (TBC1D24, AUC = 0.798; TRIM67, AUC = 0.711; ZDHHC9, AUC = 0.810; QRSL1, AUC = 0.801)." (PMID 37875591, 2023).
dengue virus infection (2 papers, 2024). "Further validation and mechanistic studies of TBC1D24, SV2B, and other screen hits can also lay the foundation for discovering host proteins and pathways that can be targeted by antiviral drugs to thwart dengue disease." (PMID 38712102, 2024).
virus infection (2 papers, 2024). "TBC1D24 and SV2B were not enriched in previous genome-scalescreens that reproducibly identified host dependency factors for direct flavivirusinfection (37, –, 41) andhave no known roles in virus infection in general." (PMID 39377586, 2024). "TBC1D24 and SV2B were not enriched in previous genome-scale screens that reproducibly identified host dependency factors for direct flavivirus infection and have no known roles in virus infection in general." (PMID 38712102, 2024).
Anxiety (1 paper, 2020). Intense feelings of nervousness, tension, or panic often arise in response to interpersonal stresses. "Mice subjected to viral-mediated knockdown of TBC1D24 in the adult hippocampus display dendritic spine loss, deficits in contextual fear memory, as well as abnormal behaviors including hyperactivity and increased anxiety." (PMID 32004315, 2020). "Mice with TBC1D24 knockdown also showed stronger preference to move at the periphery of the arena, indicating increased anxiety." (PMID 32004315, 2020).
Ataxia (1 paper, 2018). Ataxia refers to impaired coordination of voluntary muscle movement. "These two mutations resulted in the severe phenotypes observed in our patient Conclusions: The identification of the novel TBC1D24 mutation and consequent complicated clinical manifestations suggest that patients with NCSE and ataxia demand more attention." (PMID 30108545, 2018).
Cerebellar atrophy (1 paper, 2023). Cerebellar atrophy is defined as a cerebellum with initially normal structures, in a posterior fossa with normal size, which displays enlarged fissures (interfolial spaces) in comparison to the foliae secondary to loss of tissue. "Biallelic mutations of TBC1D24 were found in an infant with EA and myoclonus, with a later finding of cerebellar atrophy in adolescence." (PMID 37008993, 2023).
Cognitive impairment (1 paper, 2020). Abnormal cognition is characterized by deficits in thinking, reasoning, or remembering. "Taken together, our study provides new insights onto the subcellular localization and function of TBC1D24 in neuron, and identifies impaired dendritic spine maintenance as a plausible key pathogenic mechanism that contributes to cognitive impairment caused by TBC1D24 gene mutations." (PMID 32004315, 2020).
colon carcinoma (1 paper, 2018). "In an IP analysis of Dsh2 from lysates of LS174T human colon carcinoma cells, TBC1d24 was detected in the Dsh2 immune-complexes, indicating that the endogenous proteins are found associated." (PMID 30154457, 2018). "IP analysis of ephrinB2 from lysates of LS174T human colon carcinoma cells showed that TBC1d24 was found in the ephrinB2 immune-complexes, indicating that an endogenous interaction exists between ephrinB2 and TBC1d24." (PMID 30154457, 2018).
Encephalopathy (1 paper, 2016). Encephalopathy is a term that means brain disease, damage, or malfunction. "Patient P08 alone did not have a mitochondrial disease, her encephalopathy with refractory malignant migrating partial seizures being linked to mutations in the TBC1D24 gene." (PMID 26742794, 2016).
infantile spasms (1 paper, 2014). A rare epilepsy syndrome characterized by onset of epileptic spasms in infants between 2 and 12 months of age, and rarely up to 24 months. "We saw a wide variety of seizure types in our cohort of individuals with TBC1D24 mutations, including generalised tonic-clonic, complex partial, focal clonic seizures, and infantile spasms." (PMID 24291220, 2014).
lung adenocarcinoma (1 paper, 2024). A carcinoma that arises from the lung and is characterized by the presence of malignant glandular epithelial cells. "cg00794055 in TBC1D24, which encodes a putative Rab35-GTPase activating protein (Rab35-GAP), was hypomethylated in lung adenocarcinoma (LUAD)." (PMID 38336771, 2024).
malignant migrating partial seizures of infancy (1 paper, 2021). A very rare severe form of epilepsy with poor prognosis that usually begins within a few weeks of birth. "TBC1D24 mutations have been reported in patients with DOORS (deafness onychodystrophy, osteodystrophy, mental retardation and seizures) syndrome, progressive myoclonic epilepsy, early infantile EE and malignant migrating partial seizures of infancy (MMPSI,)." (PMID 33886577, 2021).
memory impairment (1 paper, 2020). "Neurons with TBC1D24 deficiency caused by shRNA-mediated knockdown or an ID-associated F251L missense mutation exhibit postsynaptic defects; while acute knockdown of TBC1D24 in the hippocampus or heterozygous F251L mutation leads to memory impairment." (PMID 32004315, 2020).
neuroblastoma (1 paper, 2021). Neuroblastoma (NB) is the most common solid, extracranial childhood tumor. "Tbc1d24 cytoophidia was observed also in SH-SY5Y, human neuroblastoma cells, indicating Tbc1d24 cytoophidia was conserved across species." (PMID 33886577, 2021). "We performed immunostaining of Tbc1d24 in Neuro2a mouse neuroblastoma cells and found that Tbc1d24 took a ring-like macrostructure in the cytoplasm." (PMID 33886577, 2021).
neuropathies (1 paper, 2020). "At least TUBGCP6, SYNE1, BPTF, KIDINS220, MYO5A, VPS13B, TBC1D24) are known to contain mutations causing various neuropathies." (PMID 32561887, 2020).
paroxysmal exercise-induced dystonia and (1 paper, 2022). "Likewise, for one variant broadening of the phenotypes related to variants in TBC1D24 was reported in 2019, now including rolandic epilepsy with paroxysmal exercise-induced dystonia and writer’s cramp (EPRPDC; OMIM #608105)." (PMID 35710456, 2022).
neurological disorders (9 papers, 2011 to 2023). "It has been reported that loss of function of OXR1, NCOA7, and TBC1D24 is associated with neurological diseases, including ASD, characterized by aberrant neurodevelopment." (PMID 37958785, 2023). "Nevertheless, new structural observations such as these are an important step towards understanding why mutations in TBC1D24 cause such a range of serious neurological disorders." (PMID 28707022, 2017). "Collectively, our findings illustrate the new role of Tbc1d24 for cytoophidia formation and stress response, illuminating a novel therapeutic approach for the neurological disorders." (PMID 33886577, 2021). "The pleiotropic effect of gene disruption is not an uncommon phenomenon in neurological disease, and initial mechanistic studies are pointing towards a key role for TBC1D24 in vesicle trafficking." (PMID 28707022, 2017).